LRATD1 (LRAT domain containing 1)
Description:
May play a role in cell morphology and motility.
Synonyms: NSE1; FAM84A; FLJ35392; PP11517
Tractability: No criterion of Open Targets' tractability assessment is met for any kind of drug.
Gene: Protein-coding gene on chromosome 2 (14,632,700 to 14,650,814, forward strand). Ensembl gene ENSG00000162981.
Subcellular location: Cytoplasm
Subcellular location (Human Protein Atlas): Nucleoplasm
Gene Ontology:
Molecular function: protein binding
Biological process: cell morphogenesis; cell motility
Cellular component: cytoplasm
Genetic constraint (gnomAD): Loss-of-function variants: 8 observed, 13.4 expected, observed/expected ratio (o/e) 0.6, 90% interval 0.35 to 1.08. The synonymous counts are far from expectation, so gnomAD's model fits this gene poorly and the ratio says little. Missense variants: 380 observed, 354.65 expected, observed/expected ratio (o/e) 1.07, 90% interval 0.98 to 1.17. Synonymous variants: 210 observed, 166.17 expected, observed/expected ratio (o/e) 1.26, 90% interval 1.13 to 1.42.
Homologues: Orthologues: chimpanzee LRATD1 (100% identical), macaque LRATD1 (99% identical), dog LRATD1 (99% identical), pig LRATD1 (99% identical), rabbit LRATD1 (98% identical), mouse Lratd1 (96% identical), rat Lratd1 (96% identical), guinea pig Lratd1 (95% identical), tropical clawed frog lratd1 (63% identical), zebrafish lratd1 (54% identical). Paralogues in human: LRATD2 (44% identical), PLAAT3 (13% identical), LRAT (12% identical), PLAAT4 (12% identical), PLAAT1 (11% identical), PLAAT2 (11% identical), PLAAT5 (10% identical).
Diseases named in the same sentence as LRATD1 in open-access papers:
LRATD1 is named in the same sentence as 17 diseases in open-access papers, as found by Europe PMC text mining. Sharing a sentence is not in itself a finding about the gene and the disease. The quoted sentences say what the papers report.
colon cancer (5 papers, 2019 to 2022). "An earlier study indicated that up-regulation of LRATD1 (previously called FAM84A) plays a critical role in the progression of colon cancer, but its biological function is still not well known." (PMID 31443641, 2019). "LRATD1 also named FAM84A has been revealed to be related to the occurrence and development of papillary thyroid cancer, liver tumor, and colon cancer." (PMID 36246400, 2022).
cancer (4 papers, 2019 to 2023). A tumor composed of atypical neoplastic, often pleomorphic cells that invade other tissues. "Cancer cell lines originating from same organ often gathered in the same cluster, such as C2 [COAD/READ-STAD-PAAD], a group of digestive system cancers whose common features were the high expression of CNKSR1, FOLH1, ADGRG1, SMAD7, LRATD1 and MVP." (PMID 32874774, 2020).
LRATD1 also shares sentences with these, for which no sentence is quoted: papillary thyroid carcinoma (4 papers); tumor (4); colorectal cancer (1); digestive system cancer (1); ischemic stroke (1); leukoplakia (1); liver cancer (1); Miscarriage (1); neuroblastoma (1); Obesity (1); pancreatic ductal adenocarcinoma (1); primary biliary cirrhosis (1); Sjogren syndrome (1); thyroid (1); unipolar depression (1).